IL6 (interleukin 6)
Diseases named in the same sentence as IL6 in open-access papers (continued):
Sharing a sentence is not in itself a finding about the gene and the disease.
Sepsis (continued). "However, we noticed significant decreases in the expression of pro-inflammatory cytokines IL-6 and IL-1β and chemokine MIP-2 in the lungs of B-1a cell-treated mice during sepsis." (PMID 30134811, 2018). "Male descendants of sepsis fathers, but not female descendants, exhibited lower plasma concentrations of IL-6, TNF-alpha, and IL-10 24 h after injection of LPS." (PMID 29988283, 2018). "Additionally, AA attenuated LPS-induced production of cytokines, such as iNOS, IL-1β and IL-6 in RAW264.7 macrophage cells and mice with experimental sepsis." (PMID 29599924, 2018). "Patients’ performance on the CERAD was influenced by IQCODE, serum levels of NSE and IFN-γ at UCI discharge, and APACHE II, while performance on MMSE was influenced by IL-6 at ICU discharge, time between sepsis diagnosis and antibiotics, haloperidol, mean blood glucose level during ICU stay." (PMID 29540719, 2018). "The suppression of HBP expression by heparin injection after the establishment of sepsis-induced AKI resulted in a reduction in renal injury severity accompanied with a significant repression of M1 macrophage activation and expression of TNF-α and IL-6." (PMID 29723248, 2018). "Analysis of variable importance measures suggested that length of current PICU stay until onset of non-infectious SIRS/sepsis and IL-6 were the most important predictors in our RF approach." (PMID 29544449, 2018). "Only TBARS and IL-6, but not the other markers, were significantly increased in the group of proven sepsis versus highly probable sepsis." (PMID 30174784, 2018). "In the past decades, several biomarkers have been proposed as diagnostic tests for the differentiation of sepsis and non-infectious SIRS, like e.g. procalcitonin (PCT) and interleukin-6 (IL-6)." (PMID 29544449, 2018). "We investigated if reduction in the serum concentration of the cytokines tumor necrosis factor α, interleukin (IL)-6 and IL-10, and the rate of change in the IL-6 level at 24 h after ICU admission were survival predictors for patients with sepsis and septic shock in a Vietnamese population." (PMID 30400775, 2018). "In our previous studies, we also found that 5-HT could increase the production of TNF-α and IL-6 in MODS, sepsis, and PPA formation." (PMID 29849496, 2018). "To evaluate if sepsis alters the function of naïve monocytes in a long-term manner, we stimulated MACS-sorted bone marrow monocytes with LPS and measured the production of TNF and IL-6." (PMID 30510555, 2018). "Commonly used biomarkers such as C-reactive protein (CRP), procalcitonin (PCT) and interleukin (IL)-6 were not adequately effective for predicting the severity and mortality of sepsis." (PMID 29282483, 2018). "Hence, in terms of clinical applications, measurement of the IL-6 level should be done upon admission, and at 24 h after ICU admission in sepsis and septic shock patients." (PMID 30400775, 2018). "Sepsis also increased IL6 and KC levels in non-running mice, and these increased levels were reduced in running mice." (PMID 28789683, 2017). "In contrast, higher day 1 levels of TNF-α, IL-6, IL-8, and CRP (p = 0.013, p < 0.001, p = 0.001, and p = 0.017, respectively), but not IL-1β (p = 0.057), were observed in patients with septic shock compared with those with severe sepsis." (PMID 28542440, 2017). "Sepsis sera contained higher levels of TNF-α, IL-6, IL-10 and VEGF compared to controls." (PMID 28086962, 2017). "We deduced that NEAT1 may be involved in the immune response in sepsis based on the close relationships between IL-6 and CXCL10 cytokines and the inflammatory response in sepsis." (PMID 29463949, 2017). "Therefore, in this study, the cardiovascular protection of oestrogen during sepsis can be mediated via the inhibitory effects on cellular NF‐κB signalling activation, leading to TNF‐α and IL‐6 release and cardiac iNOS induction." (PMID 28714586, 2017).
Sepsis (continued). "The high-susceptibility of sepsis-surviving mice to L. pneumophila infection was not accompanied by changes in the production of pro-inflammatory cytokines, such as TNF and IL-6." (PMID 28374774, 2017). "We found a significant higher level of IL-6 in non-surviving animals, suggesting IL-6 to be a potential biomarker predicting death in sepsis." (PMID 29204105, 2017). "Our findings demonstrated that WK2-16 attenuated both the circulating IL-6 and TNF-α levels in the early stage of sepsis, implying that it could be used as a potential and attenuative therapeutic agent in sepsis." (PMID 28661460, 2017). "Furthermore, sepsis sera compared to healthy sera contained higher levels of TNF-α, IL-6, IL-10 and VEGF but a lower concentration of EGF." (PMID 28086962, 2017). "The ongoing systemic activation of inflammatory biomarkers such as CRP, interleukin-6 and PCT during sepsis and septic shock may be an explanation of their correlation with PTX-3 levels in affected patients." (PMID 28793880, 2017). "In summary, our data demonstrated that IRE1-NF-κB pathway was obviously activated by ER stress during sepsis and contributed to the septic AKI through enhancing the production of pro-inflammatory cytokines (TNF-α, IL-1β and IL-6) in the renal proximal tubular epithelial cells." (PMID 28430592, 2017). "In addition, enhanced sepsis severity was also demonstrated by Scr (kidney injury), ALT (liver injury) and cytokines (TNF-α, IL-6 and IL-10) at 18h post-CLP." (PMID 28750040, 2017). "Aberrant upregulation and activation of pro-inflammatory cytokines and chemokines, including TNF-α, IL-1β, IL-6, IL-8, CCL5, and CXCL8, has been correlated with the progression of chronic inflammatory diseases, such as tumor, sepsis, rheumatoid arthritis, psoriasis, and cytotoxicity." (PMID 29045468, 2017). "Sera collected on day four from patients with severe sepsis harbored significantly higher concentrations of TNF-α (5.7 vs. 0.7 pg/ml, P < 0.001), IL-6 (24.8 vs. 3.8 pg/ml, P < 0.001), and IL-10 (30.0 vs. 11.9 pg/ml, P = 0.040) than sera collected from healthy controls." (PMID 28086962, 2017). "We profiled cytokine interleukin-6 (IL6) in addition to chemokines interleukin-8 (IL8) and monocyte chemoattractant protein-1 (MCP-1/CCL2), which have been shown to be highly induced in many inflammatory diseases including sepsis." (PMID 28726766, 2017). "We investigated the effects of 24 h delayed normobaric oxygen (NBO2) and HBO2 treatment on the endogenous production of the inflammatory markers interleukin (IL)-6, tumor necrosis factor (TNF)-α and IL-10, and on mortality in rats with cecal ligation and puncture (CLP) induced sepsis." (PMID 29204105, 2017). "Cytokines like TNF-α, IL-1 and IL-6 are elevated during sepsis, but they do not possess sufficient sensitivity or specificity for the development of clinical markers." (PMID 28794881, 2017). "High levels of IL-6 in non-surviving animals with sepsis suggest that IL-6 is a potential biomarker." (PMID 29204105, 2017). "The therapeutic potential of the mutant peptides in the clinical treatment of LPS-induced sepsis was reflected their ability to bind LPS directly and inhibit LPS-induced TNF-α and IL-6 release both in vitro and in vivo, promoting the survival rate of mice with endotoxemia." (PMID 28054660, 2017). "Interestingly, in a murine model of polymicrobial sepsis, inhibition of the PI3K pathway increased serum IL1-β, IL-6 and TNF-α levels and decreased the survival rate of septic mice." (PMID 28545453, 2017). "There was no statistical significance on the levels of IL-1β, IL-6, IL-2sR and IL-10 in sepsis-non AKI group compared with the control." (PMID 28296904, 2017). "TNF-α, Il-1β, and IL-6 are not considered to be “gold standard” biomarkers of sepsis due to their short half-life." (PMID 28367457, 2017). "Moreover, significant lower levels of TNF-α, IL-6, bacterial loads, MPO, and ROS were discovered in the KO-CLP sepsis group in contrast to the WT-CLP sepsis group." (PMID 28694565, 2017).
Sepsis (continued). "In patients with septic AKI, the levels of TNF-α, IL-1β, IL-6, IL-2sR and IL-10 were significantly increased, while the levels of IL-8 was significantly decreased compared with sepsis patients without AKI." (PMID 28296904, 2017). "Therefore, during sepsis IL-1 promotes IL-6 and TNF whereas after exercise IL-6 promotes IL-10 and interleukin-1 receptor antagonist (IL-1ra)." (PMID 31011016, 2017). "The injection of rSj-Cys significantly reduced the production of inflammatory cytokines including TNF-α, IL-6 and IL-1β compared to mice with sepsis without treatment." (PMID 28482922, 2017). "Nevertheless, in sepsis with AKI, plasma NGAL and tumor necrosis factor alpha (TNFα) were already elevated at 6 hours without changes to serum creatinine and blood urea nitrogen, while IL-6 and IL-10 are increased only after 24 hours." (PMID 26880194, 2016). "In addition, IL-6, IL-1β, and TNF-α had a central role in activating cytokine cascade response in sepsis and partly involved in pathogenesis of MOF." (PMID 28042205, 2016). "Plasma C-reactive protein, interleukin-6, and interleukin-8 concentrations are higher in sepsis patients with neutropenia than in those without." (PMID 27077648, 2016). "Since transfection of let-7b-5p mimic could suppress IL-6 and TNF-α production of CB monocytes, regulation of let-7b-5p has the potential to play a role in neonatal sepsis control." (PMID 28066425, 2016). "Our findings may also be in line with previous observations of higher plasma levels of type II PLA2 in sepsis patients, which significantly correlated with TNF-α, IL-6 and IL-8 levels." (PMID 26927094, 2016). "Notably, one study showedthat DEX decreased the inflammatory response in ICU patients with severe sepsis morethan did propofol infusion, when TNF-α,IL-1, and IL-6 were used as endpoints of inflammation." (PMID 26909786, 2016). "Anemia in sepsis is observed frequently and has a multifactorial etiology, including a decrease in production of erythropoietin due to inflammatory cytokines release, such as tumor necrosis factor (TNF-α), interleukin-1 (IL-1), and interleukin-6 (IL-6)." (PMID 27737630, 2016). "In addition, H1R−/−/H2R−/− mice exhibited lower levels of IL-1β, IL-6, and MCP-1 mRNAs in lung, liver, and kidney tissues as compared with WT following sepsis." (PMID 27822777, 2016). "In a murine CLP model of polymicrobial sepsis, IL-17A from γδT cells was detected, but its depletion led to a decrease in bacteremia and reductions in systemic proinflammatory cytokines (TNF-α, IL-1β, and IL-6) and chemokines." (PMID 27334720, 2016). "Concentrations of TWEAK (but not GITRL) were further decreased in patients with sepsis and correlated with routinely used markers of inflammation and bacterial infection such as C-reactive protein, procalcitonin and Interleukin-6." (PMID 27124414, 2016). "Finally, miR-23b was reported to play an important role in progression of sepsis by inhibiting the expression of NF-κB, TNF-α, IL-6, ICAM-1, E-selectin, and VCAM-1." (PMID 26761003, 2016). "In both SM and sepsis, a variety of toxins triggers the activation of MAPK and NFκB signalling pathways to induce the release of host immune factors that include cytokines, such as TNF, IL‐6, IL‐1, oxygen free radical." (PMID 27042299, 2016). "The mRNA-levels of claudin-1, occludin and E-cadherin were significantly higher during sepsis, and septic animals curatively treated with anti-IL-6 did not display this increase in mRNA levels." (PMID 27044016, 2016). "However, CC homozygous patients showed higher PaO2/FIO2, and lower sepsis-related organ failure assessment (SOFA) score, serum IL-6 levels and mortality at 30 days." (PMID 27834822, 2016). "The limitations placed on study power by multiple-association testing may in part account for our failure to replicate well-validated correlates of mortality in sepsis (in particular, TNF, IL-6, and IL-10)." (PMID 27170644, 2016).
Sepsis (continued). "IL-6 and IL-8 levels were found to be significantly higher in the serum of patients with severe sepsis compared to those without, while IL-10 was significantly lower in the EBC of patients with both severe sepsis and severe CAP, compared to those without." (PMID 28702287, 2016). "Besides the EE increases the survival of animals submitted to the lethal sepsis, activity possibly related to a decrease in TNF-α and IL-6 production and a consequent inhibition of systemic inflammation." (PMID 27630733, 2016). "Increased concentrations of both proinflammatory (e.g., tumor necrosis factor [TNF], interleukin-6 [IL-6], and IL-8) and anti-inflammatory (e.g., IL-1Ra, IL-10, and high IL-10/TNF ratios) cytokines in patients with sepsis have been previously demonstrated to predict mortality." (PMID 27170644, 2016). "Biomarkers such as IL-6 and CRP etc. are widely studied in the diagnosis and treatment of sepsis." (PMID 26599367, 2015). "The distribution of haplotype of the TGF-β, TNF-α, IL-2, IL-4, IL-6 and IL-10 genes were studied in patients with sepsis and non-sepsis." (PMID 26561011, 2015). "Therefore, we investigated blood IL-1β, IL-6, IL-4, IL-5, IL-10 and IFN-γ, which play important roles in sepsis." (PMID 26586517, 2015). "IL-6, and CRP, etc. serve as biomarkers, which may aid clinical decision-making and predicting sepsis-related outcomes." (PMID 26599367, 2015). "Increased values for IL-1β, IL-6, IL-10 and CXCL-2 were also observed in all volatile anesthetic sepsis groups compared to isoflurane-sham animals (all P <0.03), and IFN-γ was increased in isoflurane + CLP compared to isoflurane-sham animals (134.2 ± 131.9 versus 12.4 ± 12.2 pg/ml, P = 0.04)." (PMID 25887642, 2015). "This small scale patient study could show that common sepsis markers PCT, CRP, IL6 and TNFα had low predictive value for early diagnosis of SIRS after cardiovascular surgery." (PMID 26263001, 2015). "Furthermore, serum OPN concentrations were closely correlated to markers of systemic inflammation in critically ill and sepsis patients, such as CRP, PCT, IL-6 and TNF." (PMID 26111529, 2015). "In the clinical sepsis group only 30% and 10% of patients had elevated CRP and IL-6, respectively." (PMID 25894336, 2015). "Moreover, neutralization of IL-17A significantly decreased the IL-6 serum levels in the morphine-treated animals at 72 hours after CLP, validating the pro-inflammatory role of IL-17A during sepsis progression." (PMID 26039416, 2015). "Although moderate level of evidence supports IL-6 to be a useful indicator for sepsis or severity, it is important to note that almost half of the studies for this cytokine do not support the use of IL-6 as a good sepsis biomarker." (PMID 26502877, 2015). "Increased plasma levels of TGF-β and IL-6 were found in early sepsis (day 1) of nonsurvivors compared to survivors." (PMID 26881062, 2015). "The best OR values for sepsis diagnosis were obtained using PCT, MR-proADM, IL-6, and TNF-α." (PMID 26635427, 2015). "All these results indicated that dexmedetomidine can inhibit the generation of inflammatory mediators such as TNF-α and IL-6 during sepsis and this effect is independent of its α2-adrenoceptor activation effect." (PMID 25929655, 2015). "This retrospective investigation analyzed the role of the cytokines IL1-β, sIL-2R, IL-6, IL-8, IL-10 and TNF-α as potential markers for major post-transplant adverse events including VOD, skin and intestinal GvHD, sepsis as well as bacterial, viral and fungal infections in 61 pediatric patients." (PMID 26315105, 2015). "Since in other studies IL-6 was reported to peak 2–4 h after the endotoxin challenge and to correlate well with fetal HRV measures in a fetal sheep model of lipopolysaccharide-induced sepsis, its possible contribution should be analyzed in more detail." (PMID 26779039, 2015). "High serum levels of CXCL10, IL-6, IL-10, TNF and IL-8 were reported in a canine sepsis model." (PMID 26222498, 2015).
Sepsis (continued). "PCT, in particular, has been reported to be superior to endotoxin, β-D-glucan, IL-6, and C-reactive protein for differentiating between bacterial infections, including sepsis, and non-bacterial infections." (PMID 26623644, 2015). "The AUCs for IL-2, IL-6 and IL-10 were 0.901 (95% CI, 0.866 to 0.930), 0.860 (95% CI, 0.821 to 0.894), 0.888 (95% CI, 0.851 to 0.918), respectively, indicating that IL-2, IL-6 and IL-10 were effective biomarkers to rule out sepsis and intracranial infection." (PMID 24887408, 2014). "The performances of IL-2, IL-6 and IL-10 to rule out the possibility of sepsis and intracranial infection are comparable with the role of CRP." (PMID 24887408, 2014). "In accordance with previous reports, plasma NGAL and IL-6 were increased by sepsis, irrespective of AKI complication." (PMID 25524453, 2014). "At day 8 of ICU treatment, the diagnostic value of presepsin was evident for all different groups of sepsis severity (for example, diagnosis of at least sepsis, presepsin AUC = 0.82), whereas IL-6, PCT, WBC and CRP did not exceed an AUC ≥0.75." (PMID 25190134, 2014). "The area under ROC curve (AUC) of cytokines, such as IL-2, IL-6 and IL-10 were 0.901, 0.86, 0.888, respectively, which was employed to rule out the diseases of sepsis and intracranial infection." (PMID 24887408, 2014). "Due to the low plasma levels of IL-6 24 h after non-severe sepsis induction, we were not able to find significant difference between WT and MyD88-deficient mice." (PMID 25084278, 2014). "When sepsis occurs, multiple redundant inflammatory cytokines are released into the blood stream, including tumor necrosis factor-α (TNF-α), interleukin-6 (IL-6), leptin, C-reactive protein (CRP) and procalcitonin (PCT), which are important for mediating the inflammatory response." (PMID 24669245, 2014). "An earlier study suggested that IL-6 levels decay more rapidly in sepsis survivors than in non-survivors over a 96 h period supporting its prognostic value." (PMID 25398383, 2014). "The local levels of IL-6 and TNF-α were also similar in WT, Nod1- and Nod2-deficient mice 24 h after severe sepsis induction (data not shown)." (PMID 25084278, 2014). "In the context of sepsis, TNF-α, IL-1β, IL-6, and IL-8 are the most frequently altered cytokines." (PMID 24795771, 2014). "But the IL-6 level is a biomarker of sepsis severity, and our data also suggested that IL-6 was higher in non-survivors." (PMID 24977412, 2014). "We report here that female hearts subjected to sepsis have a greater activation of Akt/eNOS, and less activation of NF-κB, which in turn results in reduced expression of the proinflammaroy cytokines TNF-α and IL-6 as well as iNOS." (PMID 24945834, 2014). "The AUCs for IL-2, IL-6, and IL-10 to rule out the possibility of sepsis and intracranial infection were bigger than CRP." (PMID 24887408, 2014). "Although its diagnostic value for acute infection is not as high as IL-6, PCT is expected to be a highly specific marker for chronic and persistent infection occurring in late phase sepsis." (PMID 25460569, 2014). "This could be due to attenuation of IL-6 production and superoxide formation and suppression of iNOS and caspase-3 expression by SEL in animals with CLP-induced sepsis." (PMID 25268350, 2014). "Previous work in a mouse model of septicemia showed that naïve splenic CD4 T cells have a dampened response to IL-6 compared to uninfected mice, indicated by a reduced ability to phosphorylate STAT1 in response to ex vivo IL-6 stimulation." (PMID 23754944, 2013). "A protective effect of IL-6 was shown in experimental endotoxemia, whereas the genetic deletion of IL-6 did not alter the mortality in a model of polymicrobial sepsis induced by cecal ligation and puncture (CLP)." (PMID 23853427, 2013). "A plasma HBP level >15 ng/ml was a better indicator of severe sepsis (with or without septic shock) than any other biomarker investigated (white blood cells, IL-6, procalcitonin and C-reactive protein)." (PMID 23883488, 2013).